RELB (RELB proto-oncogene, NF-kB subunit)
Diseases named in the same sentence as RELB in open-access papers (continued):
Sharing a sentence is not in itself a finding about the gene and the disease.
prostate carcinoma (38 papers, 2005 to 2025). A carcinoma that arises from epithelial cells of the prostate gland. "Pretreatment with 1-alpha, 25-dihydroxyvitaminD suppresses increased levels of RelB caused by radiation therapy in prostate cancer cells expressing the vitamin D3 receptor." (PMID 34943029, 2021). "In prostate cancer, nuclear localisation of RelB is associated with higher grade tumours and the treatment of prostate cancer cells with androgens induces accumulation of nuclear p52." (PMID 30347849, 2018). "The level of nuclear RelB correlates with a patient’s Gleason score, suggesting that RelB expression levels are associated with prostate cancer progression." (PMID 27153093, 2016). "In prostate cancer, several studies have reported that both RelB and p65 may be putative prognostic biomarkers associated with disease progression." (PMID 26186215, 2015). "It is reasonable to suggest that such a mechanism could exist in prostate cancer, since the risk association of p65 was lost in double positive nuclei unless the frequency of p65 was at least twice as high as that of RelB." (PMID 26186215, 2015). "To evaluate the biological role of both NF-κB pathway activities, we correlated the nuclear localization of p65 or RelB with clinical parameters and risk of biochemical recurrence to better undrstand the potential role of the NF-κB pathway crosstalk in prostate cancer progression." (PMID 26186215, 2015). "Indeed, we did observe that RelB activity in prostate cancer tissues decreased the risk of recurrence associated with p65 nuclear localization, suggesting that RelB may interfere with the pro-tumoral function of the classical pathway." (PMID 26186215, 2015). "RelB also contributed to cancer immune evasion by inhibiting T cell immunity via the amplification of PD1/PD-L1 mediated immune checkpoint in prostate cancer." (PMID 37388242, 2023). "Beyond DLBCL, close relation between oxidative stress and RelB activity has also been reported in prostate cancer cells." (PMID 35203557, 2022). "Here, we describe that RelB participates in the immune evasion of prostate cancer (PCa) via cis/trans transcriptional upregulation of PD-L1." (PMID 35177112, 2022). "The expression of RelB in normal and prostate cancer cells serves as a central regulator for their opposing responses to radiotherapy." (PMID 33923601, 2021). "SOD2 induction by RelB is an important mechanism for prostate cancer cells acquiring radioresistance." (PMID 34943029, 2021). "Wei and colleagues also demonstrated that the inhibition of RelB in prostate cancer cells decreased cell viability." (PMID 33923601, 2021). "For instance, RelB expression in prostate cancer cells promotes epithelial-to-mesenchymal transition (EMT) and negatively correlates with the survival of prostate cancer patients." (PMID 31658669, 2019). "The level of nuclear RelB expression correlates with prostate cancer patient’s Gleason score, suggesting that RelB is involved in prostate cancer progression." (PMID 30473630, 2018). "RelB is a crucial factor in the differential radiosensitization effects of ascorbic acid in prostate cancer cells and normal prostate epithelial cells." (PMID 29983639, 2018). "RelB is reported as a crucial positive regulator of cell survival in multiple tumors, such as multiple myeloma, chronic lymphocytic leukemia, and prostatic cancer." (PMID 30473630, 2018). "RelB exerts a radio-protective role in aggressive prostate cancer cells through the induction of the manganese superoxide dismutase (MnSOD) gene." (PMID 30473630, 2018). "In our previous studies, we found that RelB silencing inhibits prostate cancer cell migration and invasion due to the reduction of Integrin β-1 expression." (PMID 29983639, 2018). "High nuclear levels of RelB and RelA have been detected in human prostate cancer and are related to a poor prognosis in patients." (PMID 30361641, 2018).
prostate carcinoma (continued). "Imatinib mesylate (Gleevec, STI571), a tyrosine kinase inhibitor, can enhance RelB nuclear translocation in androgen-responsive LNCaP prostate cancer cells." (PMID 29983639, 2018). "In prostate cancer, RelB is highly expressed in androgen-independent prostate cancer cells and is correlated with a more aggressive phenotype." (PMID 29983639, 2018). "The RelB:p52 dimer was shown to confer radio-resistance to prostate cancer cells by upregulating the expression of the antioxidant enzyme manganese superoxide dismutase (MnSOD)." (PMID 30061500, 2018). "STI571, a tyrosine kinase inhibitor, enhances RelB nuclear translocation in LnCaP prostatic cancer cells." (PMID 30473630, 2018). "We have reported the RelB silencing in the androgen-independent prostate cancer cell line DU145 significantly affects cell survival." (PMID 29983639, 2018). "RelB silencing in RM-1 prostate cancer cells inhibits Bcl-xL expression and enhances radiosensitivity by regulating radiation-induced apoptosis." (PMID 29983639, 2018). "Recently, a role for RelB was suggested in the therapy resistance of prostate cancer, which was explained by RelB-dependent induction of MnSOD." (PMID 27047795, 2016). "RelB was shown to promote tumorigenicity of prostate cancer cells partly due to regulating IL8 levels." (PMID 27764181, 2016). "This has not been evaluated in this study but needs to be defined if p65 and RelB are to be used as biomarkers in prostate cancer." (PMID 26186215, 2015). "The precise mechanism by which RelB could exert its suppression on p65 in prostate cancer cells still remains to be elucidated, and additional studies are required to further investigate the underlying role of RelB and the alternative pathway in prostate cancer." (PMID 26186215, 2015). "Depletion of RelB was reported to alter the viability of Hodgkin lymphoma cell lines and suppress the tumorigenicity of prostate cancer cells." (PMID 24533079, 2014). "The synthesis of GD1a is mainly regulated by ST3Gal II, and the expression of ST3Gal II is regulated by NF-κB, mainly by RelB, in castration-resistant prostate cancer cell lines." (PMID 22347453, 2012). "We previously reported that ST3Gal II was up-regulated in human castration-resistant prostate cancer cells and that the expression of ST3Gal II is regulated by NF-κB, mainly by RelB." (PMID 22347453, 2012). "A recent study revealed that RelB plays an important role in prostate cancer growth in vivo, suggesting that the NF-κB alternative pathway contributes to the progression of prostate cancer." (PMID 22216095, 2011). "To this end, we are presently expanding the analysis to more clearly define the role of RelB in prostate cancer progression." (PMID 16205698, 2005). "The alternative NF-kappaB subunit RelB dampened the effects of ionizing radiation by stimulating expression of the mitochondria-localized antioxidant enzyme manganese superoxide dismutase in prostate cancer." (PMID 37388242, 2023). "The NF‐κB2/p52/RelB pathway represents a major alternative route of NF‐κB signaling, which has been involved in drug resistance in myeloma and prostate cancer." (PMID 34957688, 2022). "The NFκB subunit RelB plays an important role in the radio-resistance of prostate cancer." (PMID 33923601, 2021). "RelB expression exhibits opposing effects of ascorbic acid in prostatic cancer and normal cells." (PMID 30473630, 2018). "Thus, RelB overexpression, which leads to high alternative NF-κB pathway activity, confers radio-resistance in prostate cancer cells." (PMID 29983639, 2018). "RelB is the most frequently detected NF-κB subunit in the nucleus of prostate cancer tissue." (PMID 27153093, 2016).
prostate carcinoma (continued). "Moreover, RelB exerts a radioprotective role in aggressive prostate cancer cells, at least partially via the induction of the MnSOD gene." (PMID 27153093, 2016). "Importantly, in prostate cancer tissue nuclear RelB was observed in more samples than p65 and there was a significant correlation between nuclear RelB and patient Gleason score." (PMID 27764181, 2016). "In addition, it was shown in an in vitro model that the inhibition of RelB expression increases the proliferation of 22Rv1 castrate-resistant prostate cancer cells and stimulates cellular autophagy." (PMID 26186215, 2015). "While the classical NF-κB/p65 pathway is known to be involved in prostate cancer progression and is associated with poor patient outcome, the role of the NF-κB /RelB alternative protein is not well defined." (PMID 26186215, 2015). "More interestingly, RankL, a cytokine that mediates differentiation of macrophages into osteoclasts, was proven to induce activation of both p65 and RelB, which may favor bone metastasis in prostate cancer." (PMID 26186215, 2015). "Interestingly, we have previously observed a binding between p65 and RelB in the 22Rv1 cell line, supporting the possibility of a direct competition between p65 and RelB in prostate cancer tissue." (PMID 26186215, 2015). "We recently demonstrated that abundant production of GD1a in castration-resistant prostate cancer cells is correlated with the high levels of ST3Gal II expression and that ST3Gal II expression is regulated by NF-κB, mainly by RelB, in castration-resistant prostate cancer cells." (PMID 22347453, 2012). "Furthermore, a recent report showed that RelB is activated in human prostate cancers in patients with high Gleason scores." (PMID 22347453, 2012). "Whether RelB or other subunits confer a more aggressive phenotype to prostatic carcinoma remains to be determined." (PMID 16205698, 2005). "RELB could upregulate PD‐L1 and facilitate immune evasion of prostate cancer." (PMID 35855654, 2022). "In order to estimate the role of RelB and the crosstalk between the classical and the alternative NF-κB pathways, we implemented a multi-staining fluorescence technique so as to quantitatively analyze the simultaneous presence of nuclear p65 and RelB in the same prostate cancer tissue cores." (PMID 26186215, 2015). "RelB suppression decreases the expression of the sirtuin SIRT3 and MnSOD, which in turn increases oxidative and metabolic stresses in prostate cancer cells." (PMID 33923601, 2021). "Previous studies show that the RelB-silencing suppresses migration and invasion abilities of DU145 prostatic cancer cells and SPC-A1 lung cancer cells by decreasing the expression of Integrin β1." (PMID 30473630, 2018). "In our current study, we found that knockdown of RelB increased the apoptosis frequency of SPC-A1 cells after exposure to 8 Gy radiation, which is in line with our previous studies in prostate cancer cells." (PMID 29983639, 2018). "Our previous studies have demonstrated that the RelB-silencing significantly attenuates the migration and invasion abilities of DU145 prostate cancer cells via the reduction of Integrin β-1 (ITGB1)." (PMID 30473630, 2018). "Many of the immune response related (e.g., IRF8, JAK3, PTGER4, RELB, IFITM3) and part of the lipid metabolism related genes (e.g., NR1H4, PPARGC1B, PLIN1, HSD17B14) were identified to be adaptive which addressed their significance for prostate cancer." (PMID 36809527, 2023). "Upregulation of the non-canonical redox-sensitive NF-kB family member, RelB, confers radioresistance in prostate cancer (PCa)." (PMID 35742868, 2022). "In our study, Ang1–7 decreased the mRNA level of RELA, RELB and REL gene, thus Ang1–7 might potentially contributes to the suppression of prostate cancer." (PMID 30361641, 2018). "For the first time p65/RelB co-distribution was assessed in prostate cancer tissues and suggested a negative crosstalk between the two NF-κB pathways in prostate cancer progression." (PMID 26186215, 2015).
prostate carcinoma (continued). "More recently, we observed an increased presence of nuclear RelB in prostate cancer tissues compared to non-neoplastic tissues, thereby suggesting that the alternative NF-κB pathway is also activated during the course of disease progression." (PMID 26186215, 2015). "This suggests that both canonical (RelA, p50) and the noncanonical (e.g., RelB, p52) NF-κB subunits can be activated in prostate cancer cells, whereas c-Rel remains inactive." (PMID 16205698, 2005). "However, in androgen-depleted LNCap cells, a hormone-sensitive prostate cancer cell line, ST3Gal II was not up-regulated in spite of the activation of RelB." (PMID 22347453, 2012). "In addition to the growth and progression of prostate cancer itself, research has been proposed that exosome PSGR1 might regulate MAPK and NF-κB signaling pathways involved in prostate cancer bone metastasis by targeting ICAM1, RELB, and IL1B." (PMID 41347146, 2025).
glioma (18 papers, 2013 to 2024). A benign or malignant brain and spinal cord tumor that arises from glial cells (astrocytes, oligodendrocytes, ependymal cells). "In some studies, the level of RElB expression was associated with glioma, non-small cell lung cancer (NSCLC), and prostate cancer." (PMID 38750159, 2024). "We have previously reported that loss of RelB in glioma significantly reduces the number and depth of invading tumor cells." (PMID 25622756, 2015). "Side-view images of 3-D collagen invasion matrices and quantification of invading cells demonstrated that loss of either RelA or RelB each resulted in a significant decrease of glioma invasive potential." (PMID 25622756, 2015). "Our studies are supported by gene expression profiles of glioma patients, which show that high level of RelB expression is associated with rapid tumor progression and low survival rates." (PMID 23451236, 2013). "In this study, we show that the NF-κB protein RelB is expressed in a particularly aggressive mesenchymal subtype of glioma, and loss of RelB significantly attenuated glioma cell survival, motility and invasion." (PMID 23451236, 2013). "Moreover, RelB is highly expressed in the mesenchymal glioma subtype and the loss of RelB significantly attenuates glioma cell survival, motility and invasion." (PMID 28598356, 2017). "Furthermore, loss of RelB in glioma cells significantly diminished tumor growth in orthotopic mouse xenografts." (PMID 23451236, 2013). "Given the association of high RelB levels with mesenchymal glioma, we next assessed whether RelB controls mesenchymal gene expression." (PMID 23451236, 2013). "Additionally, analysis of the National Cancer Institute’s REMBRANDT (Repository of Molecular Brain Neoplasia Data) database showed that increased RelB expression strongly correlates with poor survival in glioma patients, whereas low RelB expression is associated with increased survival." (PMID 23451236, 2013). "Therefore, we focused our studies on U87 cells and tested whether loss of RelB impacted the growth and survival of glioma tumorspheres." (PMID 23451236, 2013). "RelB has also been shown to promote proliferation of glioma-initiating cells as well as tumor growth and invasion." (PMID 34198987, 2021). "For example, RelB is involved in the regulation of cell cycle and can predict good prognosis in glioma." (PMID 32879628, 2020). "To date, roles for RelB and p52 reported in the literature appear mostly circumscribed to instances of pluripotent neural stem cells, transformed cells, such as glioma/glioblastoma, and several reports of expression in activated microglia." (PMID 31143184, 2019). "RelB and p52 are also reported to function in driving tumor progression in glioma cell lines and is correlated with invasive potential." (PMID 31143184, 2019). "Recently, the prognostic significance of RelB levels has also been shown for patients with grade III and IV gliomas, whereby low RelB levels were associated with longer OS35." (PMID 31586084, 2019). "Bioinformatics analysis also suggests that MMPs family genes are positively correlated with RelB in glioma tumorigenesis." (PMID 30473630, 2018). "A role for non-canonical NF-κB signalling in GSC self-renewal was also suggested by the independent observation that knockdown of RelB blocks the self-renewal activity of patient-derived glioma-initiating cells." (PMID 28598356, 2017). "RelB promotes glioma cell survival and proliferation, and controls invasion independently from RelA." (PMID 27153093, 2016). "Together, these results suggest that RelB inhibits apoptosis to enhance glioma cell growth and survival." (PMID 23451236, 2013). "We identify a critical role for RelB in controlling mesenchymal gene expression and driving oncogenesis in glioma." (PMID 23451236, 2013).